CD24 (CD24 molecule)
Diseases named in the same sentence as CD24 in open-access papers (continued):
Sharing a sentence is not in itself a finding about the gene and the disease.
breast cancer (continued). "Notably, the CD79A+CD24-PANCK+-BCSCs subpopulation with poor breast cancer prognosis in this study was strongly associated with CD8+ T-cell exhaustion and the formation of an immunosuppressive tumor microenvironment." (PMID 38066053, 2023). "Notably, human epidermal growth factor receptor 2 (HER2)-positive breast cancer cells highly express CD24, and CD24 knockdown increases the susceptibility of these cells to lapatinib, a HER2 inhibitor." (PMID 37894750, 2023). "In breast cancer, higher CD24 expression is significantly associated with a lower overall and disease-free survival rate, which suggests that CD24 is an efficient prognostic factor, closely related to clinicopathological factors, including lymph node infiltration and TNM staging." (PMID 36231025, 2022). "Activation of SDF-1/CXCR4 signalling may increase the phosphorylation of 60 proteins associated with the migration and invasion of CD44+CD24− CSCs in breast cancer." (PMID 35563449, 2022). "In a breast cancer study, CTC subsets were selected for EpCAM negativity, positivity for stem cell markers (CD44+/CD24−) and combinatorial expression of uPAR/intβ1 because downregulation of these two markers has been directly implicated in breast cancer dormancy." (PMID 34026650, 2021). "CD24 functions in cell adhesion and signaling, where high expression is associated with increased proliferation and invasion in pancreatic, colorectal and lung cancer but decreased proliferation and invasion in breast cancer cells." (PMID 33906633, 2021). "Thus, a higher frequency of CD44-/CD24- tumor cells was associated with worse survival of breast cancer patients following standard therapies." (PMID 34318746, 2021). "CD44+/CD24- has been associated with breast cancer resistance to ionizing radiation." (PMID 33680952, 2020). "It has been reported that CD24 is highly expressed and interacts with the inhibitory receptor sialic acid‐binding Ig‐like lectin 10 (Siglec‐10), which is expressed by tumor‐associated macrophages to promote immune evasion in ovarian cancer and breast cancer." (PMID 32394616, 2020). "Our results suggest that higher CD24 expression may be associated with malignant transformation and progression in breast cancer biology." (PMID 32544183, 2020). "Furthermore, we assessed the breast cancer-associated stem cell clone (CD44+/CD24-) and endothelial mesenchymal transition gene expression in relation to treatment with TQ, PTX, and their combination." (PMID 31968657, 2020). "Furthermore, TQ was found to significantly decrease breast cancer-associated stem cell clone (CD44+/CD24-cell) in both MCF-7 and T47D cells." (PMID 31968657, 2020). "Similarly, our results showed that the CD44+/CD24–/low BCSCs from HER2-negative breast cancer cells were associated with HER2 and EGFR overexpression and the radioresistant phenotype." (PMID 29464036, 2018). "Here, the next question is whether the poor prognostic impact of CD24 is linked to general aggressiveness of cancer cells or specifically of tamoxifen-resistant breast cancer cells." (PMID 29416796, 2018). "From our results, we speculate that the overexpression of H19 in malignant CSCs of breast cancer contributes to reduction in CD24 expression and causes the invasive phenotype." (PMID 30410672, 2018). "In addition, TQ, GCB and their combination depleted breast cancer associated stem cell (CD44(+)/CD24(−)/(low)) clone within MCF-7 and T47D cells by 3.8% to 27.5%." (PMID 30076320, 2018). "Expression profiling revealed 780 genes for which the expression level was affected by the loss of DIP2C, including the tumour-suppressor encoding CDKN2A gene, the epithelial-mesenchymal transition (EMT) regulator-encoding ZEB1, and CD44 and CD24 that encode breast cancer stem cell markers." (PMID 28716088, 2017).
breast cancer (continued). "Furthermore, high CD44 and low CD24 expression, characteristics associated with the breast cancer stem cell phenotype and the EMT state, was revealed in DIP2C KO cells, with potential implications for treatment and metastasis ability." (PMID 28716088, 2017). "Interestingly, some reports also showed that CD24 overexpression is associated with progression of breast cancer." (PMID 26830684, 2016). "Based on the association of CD24 overexpression with clinicopathological features and patient survival in breast cancer, the mechanism underlying CD24 overexpression was investigated using breast cancer cell lines." (PMID 26444008, 2015). "Furthermore, in human tumors, the highest STAT3 activity is found in CD44−/CD24+ breast cancer cells, markers associated with tumor-initiating capability, and EMT." (PMID 25699542, 2015). "There may be a special role for HER2 (EGFR) as molecule associated with CD24 which together with phosphorylated Akt promotes breast cancer cell survival." (PMID 26626416, 2015). "Moreover, the trend towards worse DMFS for patients with CD24-high breast cancer of the TNBC subtype indicated the association of CD24 with distant recurrence, suggesting the possible role of CD24 in promoting metastasis in the TNBC subtype." (PMID 26444008, 2015). "Furthermore, CD24 gene expression was associated with histone acetylation independent of DNA methylation, suggesting its epigenetic regulation in breast cancer." (PMID 26444008, 2015). "CD24 expression was significantly correlated with the presence of LN metastasis (P < 0.001), higher pN type (regional lymph nodes) (P = 0.006) and more advanced pathological stage (P = 0.020), suggesting that high CD24 expression is associated with more aggressive breast cancer." (PMID 26444008, 2015). "We have shown that loss of WISP2 expression in breast cancer cells leads to acquisition of the CD44+/CD24− phenotype, ALDH+ expression, upregulation of the ABCC2 drug efflux pump expression known to be associated with less differentiated cells and stem cells, although they lack SP cells." (PMID 24498388, 2014). "A previous meta-analysis investigating the relationship between CD24 expression and prognostic parameters in different carcinomas suggested CD24 expression was associated with lymph node metastasis in breast cancer and advanced clinical stages in urothelial carcinomas." (PMID 25503963, 2014). "Psoriasin and CD24 expression in breast cancer has been associated with a poor prognosis." (PMID 23300877, 2012). "Recently, the upregulation of VEGF-A and CD24 gene expression by the tGLI1 (truncated glioma-associated oncogene homolog 1) transcription factor was shown to contribute to the aggressive behavior of breast cancer cells." (PMID 23300877, 2012). "Furthermore, both psoriasin and CD24 have been associated with an unfavorable prognosis for patients with breast cancer." (PMID 23300877, 2012). "High CD44high/CD24- ratios have been associated with the claudin-low breast cancer subtype." (PMID 21952072, 2011). "Moreover, a high CD44 low CD24 expression profile in breast cancer cell lines has been associated with a putative breast cancer initiating cell phenotype." (PMID 20591176, 2010). "Association of CD44/CD24 phenotypes with breast cancer subgroups." (PMID 18559090, 2008). "We could thereby demonstrate an association between the presence of CD44+/CD24- tumor cells and a basal-like subgroup of breast cancer." (PMID 18559090, 2008). "For instance, a phase II trial involving 257 patients indicated that CD24-type alanine/valine single-nucleotide polymorphisms could predict pathological complete response (pCR) following neoadjuvant chemotherapy in primary breast cancer and modulate the host’s antitumor immune response." (PMID 40486886, 2025). "Regrettably, the ceRNA regulatory network associated with CD24 in breast cancer remains unclear." (PMID 36882451, 2023).
breast cancer (continued). "A pioneering study has indicated that CD24 is a significant marker linked to tumor metastasis, increased cell proliferation, motility, and invasiveness of abnormal fat accumulation in the body, and is associated with poor clinical outcomes in breast carcinomas." (PMID 35927653, 2022). "CD24 was specifically overexpressed in the tumor compartment, orchestrates a novel innate immune checkpoint through interaction with the inhibitory receptor sialic acid-binding Ig-like lectin 10 (Siglec-10) on tumor-associated macrophages in primary ovarian and breast cancer samples." (PMID 34215720, 2021). "In oesophageal and breast cancer cells, IL-6 exposure has been shown to promote mesenchymal/fibroblastic morphology, migration and invasion in vitro and in vivo, associated with reduced CD24, KRT19, EpCAM and E-cadherin expression and increased vimentin, N-cadherin and MMP9 levels." (PMID 34361105, 2021). "First, a retrospective analysis of CD44-/CD24- breast cancer cells in tissue specimens from patients enrolled from three academic medical centers was performed to investigate the potential associations between the frequency of CD44-/CD24- cells and postoperative tumor metastasis." (PMID 34318746, 2021). "We conclude that CD24+CD90+CD45− cells of the MMTV- PyMT mouse model possess an upregulated proteolytic signature which could very well represent a functional hallmark of metastatic TICs from mammary carcinomas." (PMID 27542270, 2016). "Using shRNA technology we were able to determine that in VEGF/c-myc mutated cancer cells and in the context of breast cancer, CD24 could serve as a key marker to identify a subpopulation of tumorigenic cancer cells, however it is not functionally involved in the induction of mitogenic pathways." (PMID 26040280, 2015). "Conversely, the expansion of circulating immunosuppressive CD19+ CD24+ CD38+ Bregs is linked to poor prognosis, underscoring the functional polarity of B cell subsets in breast cancer." (PMID 41364090, 2026). "The pretreatment and posttreatment levels of CD44, CD24, miR590-3p, miR599, and miR399-3p in breast cancer subtypes." (PMID 40587726, 2025). "It has been demonstrated that activated NK cells are capable of preferentially killing the CSC populations in breast cancer (CD24−/CD44+), pancreatic cancer (CD24+/CD44+), and glioblastoma (CD133+)." (PMID 41346579, 2025). "LUCAT1 is overexpressed in the BCSC population (CD44+/CD24-) compared to the bulk of the breast cancer cells." (PMID 41181715, 2025). "In breast cancer, estrogen-reactive elements (EREs) in the CD24 promoter inhibits CD24 expression through recruiting estrogen receptor α." (PMID 40486886, 2025). "Through a comprehensive multi-omics strategy, we systematically characterized the biological and clinical significance of MUCL1+CD24+ cells in breast cancer, and we used multiplex immunohistochemistry to confirm the poor role of MUCL1+CD24+ cells." (PMID 41142825, 2025). "We note significant upregulation of genes such as EFNA1, PTMA, SPINT2, and CD24, which have previously been indicated in increased tumor aggression and driving the transition to invasive forms of breast cancer." (PMID 39801521, 2025). "Clark and colleagues were among the first to identify that CD44+CD24−/low breast cancer CSCs were capable of initiating tumours, whereas CD44+CD24+ cells were virtually incapable of forming tumours." (PMID 40665579, 2025). "Anti-CD24 antibodies were immobilized in the microtiter plate to capture breast cancer cell line MCF7-derived EVs, followed by the introduction of anti-CD9 mAuNHs as detection probe into the assay." (PMID 41404198, 2025). "Our study reported a tumor cluster (C4 subgroup) with double-positive status of CD24 and MUCL1 in ER+ breast cancer, which was strongly associated with tumor metastasis." (PMID 41142825, 2025).
breast cancer (continued). "This integrative approach, spanning molecular to imaging analyses, provides novel insights into both the biological drivers and clinical implications of MUCL1(+) CD24(+) cells in breast cancer progression." (PMID 41142825, 2025). "In breast cancer, siRNA-mediated CD24 down-expression inhibited phosphorylation of p38, thereby improving the efficacy of doxorubicin therapy." (PMID 40486886, 2025). "Flow cytometry analysis revealed a decrease in the breast cancer stem cell population (CD44+CD24‐) in MDA‐MB‐231 cells from 95.5% to 76.5%, while in BT‐549 cells, the percentage remained nearly constant (62.1%–61.2%)." (PMID 40059964, 2025). "The expression levels of cancer stem cell genes CD44, CD24, and related miRNAs miR590-3p, miR599, and miR399-3p were aimed to be investigated before and after neoadjuvant therapy in breast cancer patients in this cross-sectional observational study." (PMID 40587726, 2025). "CD24-CAR-T cells had strong anti-tumor activity against CD24-positive breast cancer cells both in vivo and in vitro." (PMID 41409286, 2025). "It has been revealed that CD24 is a highly expressed anti-phagocytic signal in ovarian cancer and breast cancer, demonstrating the therapeutic potential for CD24 blockade in cancer immunotherapy." (PMID 40725081, 2025). "For instance, transplantation into CD44+/CD24−/ALDH1+ CSCs from breast cancer into mouse mammary fat pads resulted in the formation of foci that closely resembled the histological features of the primary tumour." (PMID 40665579, 2025). "CD44+CD24−/low cells account for 11%–35% of breast cancer cells, suggesting that they are a small but essential subpopulation of stem cells responsible for maintaining tumour heterogeneity and treatment resistance." (PMID 40665579, 2025). "CD24 is significantly overexpressed in various types of cancer, including breast cancer, ovarian cancer (OC), and pancreatic cancer." (PMID 40486886, 2025). "In contrast, we have identified miRNA biomarkers from HER2+ and CD24+ plasma EV subpopulations for the classification of early-stage breast cancer." (PMID 40405296, 2025). "Our research provides pioneering insights into the pro-tumor effects and potential clinical applications of MUCL1(+) CD24 (+) cells in ER+ breast cancer." (PMID 41142825, 2025). "Previous studies have shown that breast cancer cells contain stem-cell-like cells that express CD44+CD24-/low marker, and compared to non-CD44+CD24-/low cancer cells, these cells possess more than 50-fold increased tumorigenic capacity." (PMID 39991585, 2025). "For example, in pancreatic cancer, CSCs are identified by combinations like CD133+/CXCR4+, CD24+/CD44+, and other profiles, while in breast cancer, they express CD24−/low/CD44+." (PMID 40422220, 2025). "Correlation heatmap analysis and protein-protein interaction (PPI) network demonstrated strong associations among TNFSF4, TP63, CD24, ESR1, and PRLR, suggesting their potential roles in HR+ breast cancer progression." (PMID 40612672, 2025). "A number of studies have shown that CD24 is an unfavorable marker in the Aldehyde Dehydrogenase 1 (ALDH1)-positive CD44+/CD24− breast cancer-initiating cells in human." (PMID 40783744, 2025). "HER2+ and CD24+ EV subpopulations contain complementary biomarkers suitable for validation in larger studies that can accurately detect early-stage breast cancer among women with BI-RADS category 4 breast lesions." (PMID 40405296, 2025). "Our previous study identified that ESA+CD44+CD24-/low breast cancer cells have stem-like cell characteristics." (PMID 39991565, 2025). "Together, these findings underscore the multifaceted and context-dependent role of CD24 in breast cancer progression." (PMID 40783744, 2025). "We also uncovered somatic mutations associated with the infiltration of CD24(+) MUCL1(+) cells, along with potential inhibitors for personalized treatment in ER+ breast cancer." (PMID 41142825, 2025).
breast cancer (continued). "In breast cancer cases, the epithelial-mesenchymal transition state is linked to a cancer stem cell-like population harboring the CD44 + /CD24- profile and has been proposed to play a critical role in metastatic progression." (PMID 40097629, 2025). "We report a 4 to 6-fold enrichment of breast cancer associated EV miRNA in both HER2 and CD24 antibody labeled sample compared to isotype antibody immunolabeled samples for the BT-474 and MDA-MB-453 spike-in models (Student’s t-test p < 0.05)." (PMID 40405296, 2025). "The pretreatment and posttreatment levels of CD44, CD24, miR590-3p, miR599, and miR399-3p in breast cancer patients." (PMID 40587726, 2025). "This study investigates the molecular expression of selected CSC markers (CD44, CD24, miR590-3p, miR599, and miR339-3p) in breast carcinoma patients before and after neoadjuvant chemotherapy (NAC)." (PMID 40587726, 2025). "The expression of CD44 and CD24 genes and miR590-3p, miR599, and miR399-3p was analyzed by qPCR in pre- and posttreatment biopsies from breast carcinoma patients." (PMID 40587726, 2025). "The pre- and posttreatment expression levels of CD44, CD24, miR590-3p, miR599, and miR399-3p by pathologic response in ER + subtype of breast carcinoma." (PMID 40587726, 2025). "The pre- and posttreatment expression levels of CD44, CD24, miR590-3p, miR599, and miR399-3p by pathologic response in TN subtype of breast carcinoma." (PMID 40587726, 2025). "In syngeneic rat models of 1AS pancreatic carcinoma and MTLy mammary carcinoma, ectopic CD24 expression accelerates both primary tumor growth and metastatic dissemination." (PMID 40783744, 2025). "Specifically, M funiformis and Species Prevotellamassilia can affect breast cancer by CD38 on IgD+ CD24‐ and HLA DR on CD33br HLA DR+ CD14‐, respectively." (PMID 39654239, 2024). "The first evidence for the presence of CSCs in solid cancers emerged from identifying CD44+/CD24-/low lineage cells in immunocompromised mice with transplanted human breast cancer cells." (PMID 38737455, 2024). "The genetic ablation and therapeutic blockade of CD24 resulted in a macrophage-dependent reduction of tumor growth and extension of survival in vivo ovarian and breast cancer models." (PMID 38360723, 2024). "The aim of this study was to investigate the effect of abnormal expression of CD24 on the proliferation, migration and invasion of breast cancer (BC) cells, and the molecular mechanism of regulating CD24 expression in breast cancer." (PMID 38914670, 2024). "For example, the expression of CD24 on breast cancer is notably higher in invasive carcinoma compared to precancerous lesions." (PMID 38881902, 2024). "Our study enabled us to investigate the potential correlation between circulating cells (CTCs, Epit-CCs and CCs) in the peripheral blood of breast cancer patients and the occurrence of distant metastases, with a specific focus on the CD24+ cells." (PMID 38806508, 2024). "We investigated the associations of reproductive factors known to influence breast cancer risk with the expression of breast stem cell markers CD44, CD24, and ALDH1A1 in benign breast biopsy samples." (PMID 38577336, 2024). "Analysis of patient specimens with breast cancer using immunohistochemistry has revealed that the expression of CD24 is more frequent (34.2%) in HER2-positive specimens compared to HER2-negative specimens (26.4%)." (PMID 38881902, 2024). "Breast cancer cells that overexpress MEG8 also showed a lower proportion of CD44 + CD24- cells, which are considered tumor-initiating cells in breast tumors, except from MDA-MB-468." (PMID 39706842, 2024). "It has been reported that CD44+ and CD24 are the major CSC markers described for invasive breast cancer cells from cell lines." (PMID 38392969, 2024). "Statistical analysis showed that both EpCAM and CD24 markers can detect HER2-positive breast cancer at Stages II, III, or IV." (PMID 39513819, 2024).